SIRT7 (sirtuin 7)
Diseases named in the same sentence as SIRT7 in open-access papers (continued):
Sharing a sentence is not in itself a finding about the gene and the disease.
vitiligo (2 papers, 2024 to 2025). Generalized well circumscribed patches of leukoderma that are generally distributed over symmetric body locations and is due to autoimmune destruction of melanocytes. "To explore the modification of SIRT7 on G6PD in vitiligo, we found that silencing of SIRT7 elevated the protein and succinylation levels of G6PD in PIG3V cells, assessing by Western blot analysis." (PMID 39092715, 2024). "In the current study, we identified that SIRT7 expression was elevated in vitiligo lesions for the first time, suggesting SIRT7 regulates vitiligo progression." (PMID 39092715, 2024). "We found that SIRT7 expression in skin tissues with vitiligo lesions was significantly increased, compared with healthy controls." (PMID 39092715, 2024). "Morover, SIRT7 levels were highly expressed in lesional skin compared with adjacent normal skin from patients with vitiligo." (PMID 39092715, 2024). "For instance, SIRT7 knockdown enhances melanin synthesis, which may hold therapeutic potential for vitiligo." (PMID 40672112, 2025). "The results suggest that SIRT7 promotes the progression of vitiligo by desuccinylating G6PD." (PMID 39092715, 2024). "Since oxidative stress initiates the loss of melanocytes, which is also affected by immune‐mediated inflammation, we hypothesized that SIRT7 may be involved in vitiligo progression." (PMID 39092715, 2024). "We found that SIRT7 was highly expressed in vitiligo skin lesions." (PMID 39092715, 2024). "Herein, we identified that SIRT7 was overexpressed in vitiligo skins." (PMID 39092715, 2024). "Silencing of SIRT7 promotes pigmentation of melanocytes by succinylating G6PD, suggesting that SIRT7‐mediated G6PD desuccinylation may promote vitiligo progression." (PMID 39092715, 2024). "Then, SIRT7 expression levels in skin tissues with vitiligo were detected using IHC." (PMID 39092715, 2024). "Taken together, SIRT7 inhibits melanin production, and may thereby accelerating vitiligo progression." (PMID 39092715, 2024). "In summary, our findings suggest that SIRT7 suppresses pigmentation of melanocytes in vitiligo progress by facilitating desuccinylation of G6PD, contributing to the targeted therapies for vitiligo." (PMID 39092715, 2024). "Next, since SIRT7 is a desuccinylase, we presented evidence that the SIRT7‐mediated desuccinylation of G6PD contributed to the progression of vitiligo." (PMID 39092715, 2024). "Oxidative stress triggers the occurrence of vitiligo, and SIRT7 has antioxidant effects; however, we found that SIRT7 was highly expressed in vitiligo, indicating that it did not serve antioxidant function." (PMID 39092715, 2024). "Here, we found that SIRT7 was highly expressed in vitiligo skin lesions, and SIRT7 promoted pigmentation of melanocytes by mediating desuccinylation of G6PD, indicating a new approach for the treatment of vitiligo." (PMID 39092715, 2024).
acute leukemia (1 paper, 2022). A clonal (malignant) hematopoietic disorder with an acute onset, affecting the bone marrow and the peripheral blood. "The chromosomal position of SIRT7 (17q25.3) is commonly altered in acute leukemias." (PMID 36230534, 2022).
adenovirus infection (1 paper, 2023). "In line with this, the results of mRFP-GFP-LC3 adenovirus infection assays revealed that SIRT7 silencing significantly reduced the formation of LC3 punctate, suggesting that SIRT7 facilitated the autophagic flux of CSCC cells." (PMID 37957720, 2023).
aging (1 paper, 2025). A developmental process that is a deterioration and loss of function over time. "This may be attributed to the decreased SIRT7 associated with skin aging in older patients, leading to reduced skin immunoreactivity." (PMID 39373316, 2025).
Allergy (1 paper, 2022). An allergy is an immune response or reaction to substances that are usually not harmful. "The results showed that lung tissue samples from the allergy group showed an increasing trend in SIRT7 expression levels compared to those from the control group (p = 0.065)." (PMID 36359214, 2022).
astrocytoma (1 paper, 2020). "Unlike the literature data, our extract reduces both Sirt6 and Sirt7 expression in astrocytoma cells." (PMID 32727075, 2020).
atrial fibrillation (1 paper, 2021). A disorder characterized by an electrocardiographic finding of a supraventricular arrhythmia characterized by the replacement of consistent P waves by rapid oscillations or fibrillatory waves that vary in size, shape and timing and are accompanied by an irregular ventricular response. "Notably, increased β-OHB levels and SIRT7 expression, decreased mitochondrial biogenesis, and increased cardiac fibrosis were detected in human atrial fibrillation heart tissues." (PMID 33558457, 2021).
B-cell acute lymphoblastic leukemia (1 paper, 2024). A neoplasm of lymphoblasts committed to the B-cell lineage, typically composed of small to medium-sized blast cells. "The SIRT7–Pax5 interplay was conserved in B cell acute lymphoblastic leukemia, where SIRT7 expression correlated with good prognosis." (PMID 39424985, 2024).
Cachexia (1 paper, 2024). Severe weight loss, wasting of muscle, loss of appetite, and general debility related to a chronic disease. "Recently, SIRT7 has been demonstrated to allow the switch-off in energy consumption in pathological conditions such as cachexia to avoid excessive BAT activation and/or WAT browning." (PMID 39683558, 2024).
calcific aortic valve disease (1 paper, 2025). "Hesperidin has been shown to prevent the development of calcific aortic valve disease via the SIRT7-Nrf2-ARE axis." (PMID 41480421, 2025).
cardiomyopathy (1 paper, 2021). A disease of the heart muscle or myocardium proper.
chronic hepatitis C (1 paper, 2017). "Then, our work is the first study conducted on a large cohort of well-characterized patients with chronic hepatitis C. It demonstrates a marked down-regulation of miR-125a in tumor tissue and a subsequent up-regulation of its oncogenic targets MMP11, SIRT7 and c-Raf." (PMID 28445974, 2017).
colitis (1 paper, 2022). Inflammation of the colon. "Immunohistochemical staining showed that SIRT7 was significantly upregulated in the colon mucosa samples from colitis-induced mice compared to those of mice in the control group." (PMID 36359214, 2022). "In our preliminary study, using an OVA-induced colitis model, we found that SIRT7 levels in the lungs were increased when inflammatory responses were induced." (PMID 36359214, 2022). "Immunohistochemical staining showed that SIRT7 was significantly downregulated in colon mucosa samples from SI-treated mice compared to those of mice in the colitis group." (PMID 36359214, 2022). "We assessed the effect of a novel selective SIRT7 inhibitor on the progression of colitis in our experimental animal model." (PMID 36359214, 2022). "The colitis group showed increased levels of inflammatory cytokines and SIRT7 in the colonic mucosa." (PMID 36359214, 2022). "The inflammatory reaction was suppressed in colitis-induced mice administered the SIRT7 inhibitor." (PMID 36359214, 2022). "We used a murine colitis model to investigate the role of SIRT7 in intestinal immunity and whether SIRT7 inhibitors could attenuate the intestinal inflammatory response." (PMID 36359214, 2022). "Considering the potent effects of SIRT7 and its function in inflammation, we hypothesized that SIRT7 is involved in colitis, especially immune-mediated intestinal inflammation." (PMID 36359214, 2022). "Mice were divided into three groups: control, colitis-induced, and SIRT7-inhibitor-treated." (PMID 36359214, 2022). "To examine whether colonic inflammation affected SIRT7 expression in the mouse colon, we performed immunohistochemical staining of the colon mucosa of colitis-induced mice." (PMID 36359214, 2022). "We further evaluated whether SIRT7 inhibitors attenuated inflammation in a colitis model." (PMID 36359214, 2022). "In our preliminary study, we confirmed that SIRT7 was elevated in the lungs of mice that induced allergic inflammation of the lung and hypothesized that a similar response would also occur in the colon mucosa that induced colitis." (PMID 36359214, 2022). "First, we did not evaluate the detailed molecular mechanisms of SIRT7 or the NF-κB pathway in colitis." (PMID 36359214, 2022).
colon adenoma (1 paper, 2021). An adenoma that arises from the colon. "Our data show that SIRT7 expression is obviously increased in human colon adenoma tissues and naturally aged male mice tissues in comparison to corresponding control groups." (PMID 34604215, 2021).
complication (1 paper, 2020). Any disease or disorder that occurs during the course of, or because of, another disease, treatment, or procedure. "Besides, except for SIRT1, there are still other members of the sirtuin family (e.g., SIRT3, SIRT6, and SIRT7) that are active in modulating vascular function, which inspires further works to investigate their associations with oxidative stress and diabetic vascular complications." (PMID 33304318, 2020).
experimental autoimmune encephalomyelitis (1 paper, 2025). An autoimmune demyelinating disease of the central nervous system that is produced experimentally in animals by the injection of homogenized brain or spinal cord in Freund's adjuvant. "Subtle immune dysregulation in SIRT7 knockout models of experimental autoimmune encephalomyelitis is characterised by impaired survival of newborn neurons." (PMID 40672112, 2025).
HIV-1 infection (1 paper, 2021). The type species of lentivirus and the etiologic agent of acquired immunodeficiency syndrome (AIDS). "Vpr proteins isolated from different HIV-1 lineages or from ancestral SIVs that infect chimpanzee, but not from HIV-2, show an ability to degrade SIRT7 in the same manner, suggesting that SIRT7 down-regulation is beneficial to HIV-1 infection." (PMID 33648539, 2021).
human papillomavirus infection (1 paper, 2025). "In addition, we observed enriched immune response related terms such as cGMP-PKG signaling pathway, TNF signaling pathway and IL-17 signaling pathway, as well as human papillomavirus infection in SIRT7-KO cells with or without GPS infection." (PMID 40636259, 2025).
hypertrophic cardiomyopathy (1 paper, 2016). A condition in which the myocardium is hypertrophied without an obvious cause. "Overall, our results provide the first evidence of an accelerated aging phenotype in SirT7−/− mice, which is consistent with a previous SIRT7 KO mouse model showing hypertrophic cardiomyopathy and a shortened lifespan." (PMID 27225932, 2016).
immune thrombocytopenia (1 paper, 2025). "In this study, we investigated the effect of SIRT7 on the balance of Th17/Treg in immune thrombocytopenia (ITP) and to elucidate the associated molecular pathways." (PMID 40672112, 2025).
infarction (1 paper, 2025). A localised pathological necrosis of tissue resulting from obstruction of the blood supply usually by a thrombus, an embolus, or vascular torsion. "Astragaloside IV, a major active compound of Astragalus, may promote angiogenesis via the silencing regulatory protein 7 (SIRT7)/vascular endothelial growth factor A (VEGFA) signaling pathway to improve brain tissue damage postcerebral infarction." (PMID 40802347, 2025).
intestinal inflammation (1 paper, 2022). "Our study demonstrated that SIRT7 inhibition attenuated the inflammatory response in the colon of mice, suggesting a possible role for SIRT7 in the pathogenesis of immune-mediated intestinal inflammation." (PMID 36359214, 2022).
ischemic stroke (1 paper, 2023). A stroke disorder caused by obstruction of blood flow to the brain, due to thrombotic (local blood clot formation) or embolic (due to a blood clot or other material traveling from another site) event. "Studies on the function of SIRT7 in ischemic stroke are scarce." (PMID 37627275, 2023). "Therefore, it is reasonable to speculate that circ-Rps5 attenuated ischemic-stroke-induced brain injury via the miR-124-3p/SIRT7 signaling pathway." (PMID 37627275, 2023).
kidney cancer (1 paper, 2023). Primary or metastatic malignant neoplasm involving the kidney. "In kidney cancer, we confirmed that SIRT7 is also an oncogenic factor." (PMID 37691108, 2023).
kidney damage (1 paper, 2022). "We found that Sirt7 deficiency attenuated AKI, which was evidenced by lower urinary excretion of both albumin and biomarkers of kidney damage, such as Hsp72, KIM-1, and SerpinaA3." (PMID 35269715, 2022).
leukopenia (1 paper, 2016). "In addition, we observed an overall decline in the physiological condition of SirT7−/− mice, including reduced circulating IGF‐1 protein, increased p16INK4 expression, altered HSC compartment, and leukopenia." (PMID 27225932, 2016).
lipodystrophy (1 paper, 2018). A congenital or acquired disorder characterized by abnormal loss or redistribution of the adipose tissue in the body. "Absence of Sirt7 leads to hyperactive, deacetylated Sirt1 causing lipodystrophy in Sirt7 knockout mice due to repression of the PPARγ gene." (PMID 29963979, 2018).
liver inflammation (1 paper, 2025). "In this study, we uncover a novel mechanism in which SIRT7-mediated deacetylation of RELA at K119 promotes liver inflammation and fibrosis." (PMID 41322258, 2025).
mantle cell lymphoma (1 paper, 2019). Mantle cell lymphoma is a rare form of malignant non-Hodgkin lymphoma affecting B lymphocytes in the lymph nodes in a region called the ``mantle zone''. "Two alkylating agents, bendamustine and a metabolite of cyclophosphamide (4-hydroperoxy-cyclophosphamide, 4-OHCY) induce H3K18 acetylation and decrease the expression of SIRT1, SIRT7, and HDAC3 in a dose-dependent manner in mantle cell lymphoma (MCL) cells." (PMID 31121824, 2019).
Metastatic cancers (1 paper, 2020). A carcinoma which has spread from the original site of growth to another anatomic site. "Metastatic cancers were found to down-regulate SIRT7 to suppress this activity of SIRT7 during metastasis." (PMID 32656073, 2020).
Myocardial fibrosis (1 paper, 2025). "According to the findings, SIRT7, by controlling YAP/ATP7A signaling, lowers cuproptosis, myocardial fibrosis, and cardiac dysfunction in hypertensive conditions." (PMID 41567643, 2025).
neuroblastoma (1 paper, 2022). Neuroblastoma (NB) is the most common solid, extracranial childhood tumor. "To elucidate the role of SIRT7 in AD, we examined Aβ42-induced toxicity in SIRT7 knockdown (KD) neuronal SH-SY5Y cells, a human neuroblastoma cell line." (PMID 36012298, 2022).
nonalcoholic fatty liver disease (1 paper, 2023). "Notably, nonalcoholic fatty liver disease (NAFLD)-associated HCC shows activation of Sirtuin 7 SE (SIRT7)." (PMID 36726725, 2023).
osteoarthritis (1 paper, 2024). A noninflammatory degenerative joint disease occurring chiefly in older persons, characterized by degeneration of the articular cartilage, hypertrophy of bone at the margins and changes in the synovial membrane. "A better mechanistic understanding of SIRT7 imbalance will be of clinical importance in developing therapies against osteoarthritis." (PMID 37676263, 2024). "SIRT7 level is reduced in degenerated cartilage of osteoarthritis patients and is insufficient to orchestrate the autophagy response that is necessary to protect chondrocytes from degeneration." (PMID 37676263, 2024). "An independent study found that Sirt7-KO mice are resistant to aging- and forced exercise-induced osteoarthritis." (PMID 37676263, 2024).
pancreatic adenocarcinoma (1 paper, 2024). "The current investigation has demonstrated that SIRT7 expression is upregulated in pancreatic adenocarcinoma tissues vs. adjacent normal tissues." (PMID 38316768, 2024). "Our analysis utilizing the GEPIA tool revealed that the expression of SIRT7 was upregulated in pancreatic adenocarcinoma (PAAD) tissue compared with adjacent normal tissue." (PMID 38316768, 2024).
papillary thyroid cancer (1 paper, 2024). "In papillary thyroid cancer, SIRT7, an NAD + -dependent histone/non-histone deacetylase, may be targetable, as it often shows increased expression; SIRT7 suppresses the transcription of DBC1, an endogenous inhibitor of SIRT1, by deacetylating H3K18Ac." (PMID 39614261, 2024).
papilloma (1 paper, 2021). A benign epithelial neoplasm that projects above the surrounding epithelial surface and consists of villous or arborescent outgrowths of fibrovascular stroma. "Compared with Sirt7+/+ mice, Sirt7+/− mice generated much larger papillomas and in greater numbers following continuous exposure of the dorsal skin to TPA." (PMID 34433808, 2021).
Parkinson disease (1 paper, 2021). A progressive degenerative disorder of the central nervous system characterized by loss of dopamine producing neurons in the substantia nigra and the presence of Lewy bodies in the substantia nigra and locus coeruleus. "SIRT6 and SIRT7 regulate TNFα, and reduced activity leads to Parkinson’s disease." (PMID 33668997, 2021).
periodontal disease (1 paper, 2022). "Although no recent data on SIRT7 and periodontal disease could be found at the time of this review, downregulation of SIRT7 is observed in carcinomas." (PMID 35630070, 2022).
premature aging syndrome (1 paper, 2022). Changes in the organism associated with senescence, occurring at an accelerated rate. "Low levels of SIRT7 were also found in induced pluripotent stem cells (iPSCs) with prolonged in vitro culture, which recapitulate several aspects reported for premature aging syndromes (for example, Hutchinson-Gilford progeria syndrome) and for somatic cell senescence." (PMID 35585284, 2022).
Right ventricular hypertrophy (1 paper, 2024). In this case the right ventricle is more muscular than normal, causing a characteristic boot-shaped (coeur-en-sabot) appearance as seen on anterior- posterior chest x-rays. "The pulmonary endothelium-specific depletion of SIRT7 increased right ventricular systolic pressure and exacerbated right ventricular hypertrophy." (PMID 38791128, 2024).
sarcopenia (1 paper, 2021). Progressive decline in muscle mass due to aging which results in decreased functional capacity of muscles. "Since SIRT7 regulates the muscle protein degradation system in old animals, SIRT7 may act against sarcopenia, which is characterized by loss of skeletal muscle mass and function." (PMID 33806509, 2021).
skin cutaneous melanoma (1 paper, 2023). "For further verification, we turned to TCGA skin cutaneous melanoma (SKCM) database to analyze the relationship between SIRT7 expression and tumor stress status." (PMID 36918544, 2023).
Thrombocytopenia (1 paper, 2025). A reduction in the number of circulating thrombocytes. "Furthermore, SIRT7 deficiency exacerbated thrombocytopenia and Th17/Treg imbalance in vivo." (PMID 40672112, 2025). "In vivo experiments demonstrated that SIRT7 knockout exacerbated thrombocytopenia and further disrupted Th17/Treg homeostasis in murine models." (PMID 40672112, 2025).